GCG (glucagon)
Diseases named in the same sentence as GCG in open-access papers (continued):
Sharing a sentence is not in itself a finding about the gene and the disease.
Insulin resistance (continued). "Additionally, the magnitude of peripheral metabolic effects, like insulin secretion, glucagon suppression, and modulation of gut hormones, can also be influenced by a patient’s existing metabolic status and degree of insulin resistance." (PMID 41010364, 2025). "In addition, increased fasting glucagon and delayed glucagon suppression have been shown to go along with insulin resistance even in subjects with normal glucose tolerance." (PMID 38681771, 2024). "As elevations in plasma glucagon concentrations are implicated with hepatic steatosis, independent of insulin resistance, these results suggest that reduced ICR is a consequence of intra-hepatic lipid accumulation rather than insulin resistance per se." (PMID 39138690, 2024). "Cellular mechanisms underlying these findings have not been investigated presently, but they may include intra-islet insulin resistance, altered glucose sensitivity of alpha cells, and hepatic glucagon resistance." (PMID 37708362, 2024). "A greater reduction in insulin resistance and glucagon levels was noted with Tirzepatide as compared to dulaglutide and semaglutide, which could potentially be a factor in improved glycaemic and metabolic results over GLP1 RAs." (PMID 38665722, 2024). "These outcomes collectively demonstrate that ginseng extract could promote insulin secretion, suppress glucagon secretion, improve pancreatic islet function, and ameliorate insulin resistance in T2DM mice." (PMID 38989151, 2024). "Studies have shown that dietary intake of propionate in humans can lead to increased postprandial plasma concentrations of glucagon, fatty acid-binding protein 4 (FABP4), and norepinephrine, which may cause insulin resistance and then increase glucose." (PMID 39194508, 2024). "We suggest that this may be related to the fact that high dietary selenium intake increases MAFLD risk by modulating dysregulation of insulin biosynthesis and secretion as well as stimulating glucagon secretion, insulin resistance and dyslipidemia." (PMID 38435294, 2024). "In probiotic group, insulin resistance, HbA1c, glucagon, leptin, and oxidative stress decreased." (PMID 39125375, 2024). "This could be due to co-existing insulin resistance masking glucagon-conferred improvements in glucose homeostasis, but further research is warranted." (PMID 38579751, 2024). "Metabolic effects of SGLT2i have also been reported, independent of their glucuretic actions, which could improve insulin resistance, suppress insulin secretion by beta cells, and stimulate glucagon secretion by alpha cells of pancreatic islets." (PMID 38528542, 2024). "Adjunctive therapy with GLP-1RA alongside insulin may provide direct and indirect benefits by increasing glucagon and reducing insulin resistance in patients with T1DM." (PMID 38962634, 2024). "In conclusion, ATMP could promote insulin secretion and inhibit glucagon secretion, effectively improve glucose tolerance and alleviate insulin resistance." (PMID 36845056, 2023). "Additionally, insulin resistance, which primarily affects peripheral tissues, can also impact alpha cell function and glucagon secretion." (PMID 37409229, 2023). "An increased glucagon/insulin ratio is another marker of insulin resistance." (PMID 37509329, 2023). "In this study, we found that ATMP could effectively improve glucose tolerance and alleviate insulin resistance by promoting insulin secretion and inhibiting glucagon secretion." (PMID 36845056, 2023). "In addition, insulin resistance-related metabolism and glucagon signaling pathway increased in T2DM (p < 0.0001)." (PMID 37298483, 2023). "After microbiota clearance, the glucagon concentration, the homeostasis model assessment for insulin resistance (HOMA-IR), and the area under the curve (AUC) of the IPGTT were decreased significantly in the TAC germ-free (TAC-GF) group in the third month as compared to the other groups." (PMID 35859583, 2022).
Insulin resistance (continued). "The insulin-resistance inducing effect of acute pain has been confirmed in many studies and attributed primarily to its effects on glucose metabolism, with elevated levels of glucagon, growth hormone and cortisol frequently observed in burn patients." (PMID 36296932, 2022). "Clinical and experimental evidence has suggested that patients with insulin resistance in T1D may have abnormal glucagon action." (PMID 35725834, 2022). "Interestingly, these genes are associated with metabolic pathways such as endocrine disorders, glucagon signaling, parathyroid hormone, and insulin resistance." (PMID 34707105, 2021). "The present study supports the potential link between hepatic fat accumulation and insulin resistance via glucagon signalling despite the lack of a proven cause–effect relationship." (PMID 33275161, 2021). "Moreover, increased fasting glucagon and delayed glucagon suppression have been shown to go along with insulin resistance in individuals with normal and impaired glucose regulation." (PMID 33828527, 2021). "Moreover, one of the mechanisms by which metformin and other biguanides mitigate insulin resistance and diabetes is through inhibiting the glucagon-stimulated cAMP/PKA pathway." (PMID 34578916, 2021). "The secretion of hypothalamic, pituitary, and counterregulatory stress hormones, such as cortisol, adrenaline, noradrenaline, and glucagon, all participate in generating a state of insulin resistance with increased hepatic glucose output and glycogen breakdown." (PMID 33463901, 2021). "Interestingly, despite normal glucagon secretion at 2 months of age alphaIRS2KO mice displayed slightly reduced body weights, insulin resistance, and reduced AKT phosphorylation in response to insulin." (PMID 33839150, 2021). "Impaired activation of GIPR and GLP-1R contributes to a decrease in the secretion of insulin and ghrelin and, on the contrary, to an increase in leptin and glucagon in the circulation, which contributes to the formation of insulin resistance in obese patients with T2DM." (PMID 33959145, 2021). "In this study, therefore, we investigated whether DCI could prevent palmitate-induced insulin resistance and prevent glucagon secretory dysfunction." (PMID 33020399, 2020). "Therefore, the aim of this preclinical study was to investigate the preventive role of DCI in insulin signaling pathways and glucagon secretion in an established model of α-cell insulin resistance." (PMID 33020399, 2020). "It suggests that lower postprandial GIP levels may prevent enhanced glucagon secretion in the early stage of insulin resistance." (PMID 32411223, 2020). "Likewise, alpha cell insulin resistance reduces postprandial glucagon suppression, and thus sustains hepatic glucose production in the postprandial state, which contributes to IGT." (PMID 32774668, 2020). "Impaired glucagon secretion after fatty meat suggests early pancreatic alpha-cell dysfunction, while higher insulin secretion after a carbohydrate meal is a compensatory mechanism for developing insulin resistance in obese subjects." (PMID 32411223, 2020). "Moreover, these patients had significantly higher fasting glucagon levels even in the face of elevated fasting plasma insulin, suggesting impaired cross-talk between α and β-cells due to insulin resistance." (PMID 30948746, 2019). "Increased fasting glucagon concentrations may be responsible of the more pronounced insulin resistance, as observed in PD+ individuals according to HOMA-IR." (PMID 30451975, 2019). "Although, in some cases, relative insulin deficiency prior to developing insulin resistance seemed to be present, glucagon was not produced in excess." (PMID 30908518, 2019). "Hyperglucagonemia, failure to suppress glucagon and increased insulin resistance could contribute to the impaired glucose regulation in subjects on statin therapy." (PMID 31546230, 2019).
Insulin resistance (continued). "In addition, acute administration of glucagon has been shown to induce insulin resistance, which would also result in an impaired glucose-lowering effect of insulin." (PMID 29558502, 2018). "Insulin resistance in pancreatic alpha cells may explain the elevations in circulating glucagon observed in db/db mice." (PMID 29038790, 2017). "We studied three pancreatic hormones (insulin, glucagon, C-peptide) related to insulin resistance." (PMID 27465935, 2017). "Furthermore, the PH supplementation also decreased plasma glucose, insulin, glucagon, and homeostasis model assessment of insulin resistance levels." (PMID 26891322, 2016). "In animal studies, increased leucine intake could improve glucose metabolism, reduce diet-induced insulin resistance and lower plasma glucagon levels and hepatic glucose-6-phosphatase expression." (PMID 26593945, 2015). "By acting on GIP receptors on adipocytes, GIP exhibits insulin mimetic properties such as elevation in glucose uptake, fatty acid synthesis, lipoprotein lipase synthesis, and reduction in glucagon-induced lipolysis; resulting in fat accumulation in adipocytes, obesity and insulin resistance." (PMID 26648813, 2015). "Moreover, induction of postprandial insulin resistance by glucagon was overcome by restoring the levels of GSH, indicating that depletion of hepatic GSH is a critical mechanism of glucagon action in inducing insulin resistance." (PMID 25961284, 2015). "Finally vildagliptin seems to reduce insulin resistance demonstrated by both reduction in serum levels of insulin and glucagon." (PMID 26170902, 2015). "Metabolic hormones (e.g., leptin, adiponectin, and glucagon), nutrient excess, systemic free fatty acids, ER stress/oxidative stress, adipose hypoxia, adipose inflammation, and so on account for the generation of insulin resistance." (PMID 23662132, 2013). "Insulin resistance leads to hyperinsulinemia, which might also have been stimulated in the studied group by the increase in plasma glucagon." (PMID 22829443, 2013). "This may explain why E2-treated mice have suppressed hyperglucagonaemia and lower insulin concentrations, as a decrease in hyperglucagonaemia improves glucagon-induced hepatic insulin resistance." (PMID 23132340, 2013). "Insulin resistance in α-cells may result in concurrently unsuppressed glucagon secretion under insulin-stimulatory conditions." (PMID 23316165, 2012). "Interestingly, glucagon/cAMP signaling pathway was known to be induced by insulin resistance in the liver." (PMID 23028378, 2012). "Secondly, glucagon may form a vicious cycle with insulin resistance." (PMID 41458542, 2025). "Since glucagon stimulates insulin release and increases hepatic glucose production, hyperglucagonaemia may contribute to the enhanced β-cell responsiveness and insulin resistance known to characterize early-onset type 2 diabetes (T2D)." (PMID 39459592, 2024). "Therefore, high dietary selenium intake may increase NAFLD risk by dysregulating insulin biosynthesis and secretion and stimulating glucagon secretion, insulin resistance, and dyslipidemia." (PMID 36864425, 2023). "The excess mortality has been hypothesized to be due to the combined effects of glucagon, growth factors, catecholamines, and glucocorticoids, leading to gluconeogenesis, inflammation, and insulin resistance, contributing to neuroinflammation and oxidative stress that exacerbates the brain injury." (PMID 35084107, 2022). "Furthermore, TD may reduce insulin resistance and increase insulin sensitivity by improving pancreatic β-cells function, increasing insulin secretion, and decreasing glucagon levels." (PMID 35725834, 2022). "Notably, the association of the glucagon–alanine index with insulin resistance was independent of liver fat content in the entire study cohort." (PMID 33275161, 2021).
Insulin resistance (continued). "It seems that lower postprandial glucagon concentration in obese women after a fat meal in our study may be an early sign of pancreatic alpha-cell dysfunction, or it may represent a counterregulatory mechanism to the development of insulin resistance." (PMID 32411223, 2020). "The glucagon concentration, in this experiment, was significantly increased and then remained stable in the following period, so as to promote the gluconeogenesis in the state of starvation and insulin resistance, maintain low and stable blood glucose level, and promote yak adaptation to starvation." (PMID 31952136, 2020). "Additionally, using KEGG mapper 77, we found that several SLC16A1-AS1 targets are involved in pathways not only related with metabolism (amino acid metabolism, glutamate metabolism, glucagon signaling and insulin resistance), but also with innate immune system response (NOD-like signaling)." (PMID 32863950, 2020). "Additionally, fasting plasma glucagon concentrations were higher in the HF (+126%; P< 0.001), HF-A (+75%; P<0.05), and HF-L (+108%; P<0.01) groups than in the SC group, indicating that insulin resistance contributes to the dysregulation of glucagon secretion in altered glycemic states." (PMID 23894285, 2013). "This is consistent with the observations that lacking α-cell mass expansion and glucagon secretion may cause secondary inability of the β-cell mass to adapt peripheral insulin resistance in mice under excessive nutrient feeding conditions." (PMID 23316165, 2012). "But as insulin resistance increases, the counter-regulatory measures within islets may become dysfunctional or overridden by high insulin levels, leading to increased α-cell turnover and ultimately more glucagon released into the circulation." (PMID 21283589, 2011). "In addition, we cannot role out that other mediators of insulin resistance such as catecholamines, glucagon or growth hormone might also have contributive effects." (PMID 19087258, 2008). "Concurrently, TIR, insulin levels, C-peptide levels, and insulin resistance (as measured by HOMA-IR) improved, while 2-hour postprandial glucagon (2h-PGlu) decreased." (PMID 42238245, 2026). "Peptide supplementation experiments in CgA-KO mice revealed that CST suppressed gluconeogenesis and enhanced glucagon regulation, whereas PST promoted insulin resistance and glucose production." (PMID 41298823, 2025). "Anthropometric measurements, lipids profile, homeostasis model assessment of insulin resistance (HOMA-IR), free thyroxine (FT4), triiodothyronine (FT3), thyroid stimulating hormone (TSH) and serum fasting glucagon were assessed." (PMID 40069760, 2025). "The liver-alpha cell axis, involving liver fat and glucagon interactions, correlates with HOMA-IR, highlighting the complex relationship between liver fat content and insulin resistance." (PMID 41446289, 2025). "FI: fasting insulin, FG: fasting glucagon, IGR: insulin:glucagon ratio, HOMA-IR: homeostatic model assessment for insulin resistance, HbA1c: glycated hemoglobin." (PMID 38665134, 2024). "In the full cohort (n = 54), augmented responses of glucagon, cortisol, and ACTH and attenuated responses of GH correlated with adiposity, dysglycemia, and insulin resistance." (PMID 37708362, 2024). "Our previous clinical study showed the effectiveness of Eriomin® in reducing fasting glucose, glucose intolerance, insulin resistance (HOMA‐IR), glycated hemoglobin (HbA1c), glucagon, C‐peptide, HSCRP, IL‐6, and TNF‐α." (PMID 37970408, 2023). "Homeostasis model assessment-insulin resistance (HOMA-IR) index demonstrated a significant reduction by 5.4-fold in the diabetic group treated by SG-loaded nanosystem and exhibited reduced glucagon level by 40.85%." (PMID 35624887, 2022). "A significant decrease in fasting glycemia (−5%), insulin resistance (−11%), ALP (−8%), glucagon (−13%), IL-6 (−14%), and TNF-α (−20%) was detected." (PMID 35796695, 2022).
Insulin resistance (continued). "Moreover, sympathetic nervous system activation raises the production of glucagon, catecholamine, cytokine and cortisol that stimulate the glucose release from liver, mobilizes circulating free fatty acids (FFAs) from adipose tissue and contributes to insulin resistance." (PMID 35784538, 2022). "Although the metabolism of liver is generally regulated by insulin and glucagon, NALFD is often accompanied by systemic insulin resistance and the insulin resistance is selective, which makes the actual metabolic state hard to predict." (PMID 34526911, 2021). "Plasma glucose, insulin, and glucagon and HOMA-IR levels were measured to assess the effects of AL supplementation on insulin resistance." (PMID 32796637, 2020). "The MAO group had worse metabolic status than the MHNW group, as indicated by higher C-peptide levels, insulin levels, glucagon levels, HOMA-IR index values, and insulin resistance rates." (PMID 32811450, 2020). "We also measured plasma insulin and glucagon levels and then calculated HOMA-IR to determine the effect of LGZG on insulin resistance." (PMID 31396097, 2019). "Accordingly, we found that chronic treatment with atorvastatin induced insulin resistance of the IR/IRS-1/AKT pathway and through this mechanism increased proglucagon gene expression and glucagon secretion." (PMID 31546230, 2019). "Considered together with our results, most data suggest that LSG provides early and ongoing significant improvement in glucagon levels in both overt clinical T2DM and subclinical insulin resistance in the obese." (PMID 27465935, 2017). "After adjusting for age gender and BMI, fasting glucagon levels were positively correlated with 2-h post-load glucose levels, the HOMA index of insulin resistance and fasting insulin levels, and were negatively correlated with IGF-1 levels." (PMID 28881681, 2017). "Pancreata from human subjects with insulin resistance showed a 2–3-fold increase in insulin/glucagon bi-hormonal cells compared with individuals without insulin resistance, especially within larger islets." (PMID 39791735, 2025). "In the summary assessment of the hypoglycemic clamp, there was no group difference between participants with and without T2D, but insulin resistance and central adiposity correlated with elevated glucagon levels." (PMID 37708362, 2024). "Another study indicated that propionate intake could increase the secretion of glucagon and fatty acid-binding protein 4 (FABP4) in both mice and humans, potentially leading to insulin resistance." (PMID 38411058, 2024). "Children and adolescents with obesity and insulin resistance have elevated concentrations of fasting plasma glucagon and GLP-1, elevated glucagon, and attenuated GLP-1 responses during the OGTT, which is paralleled by lower estimates of insulin sensitivity and altered β-cell function." (PMID 38087928, 2024). "Taken together, altered glucose-dependent responses of both glucagon and the HPA axis seem to be features of overweight and insulin resistance that potentially may contribute to the development of T2D." (PMID 37708362, 2024). "As elevations in plasma glucagon are a metabolic disturbance of hepatic steatosis, independent of insulin resistance or glucose tolerance, these observations likely describe reduced ICR as a consequence of hepatic steatosis." (PMID 39138690, 2024). "The recruitment of subjects stratified by insulin sensitivity allowed us to uniquely examine the combined effects of obesity and insulin resistance on glucagon, GLP-1, and GIP secretion, which has not been previously characterized in pediatric studies." (PMID 38087928, 2024). "Although high glucagon levels are associated with insulin resistance, given the relatively higher glucagon levels in LEN group compared to CTL, we did not observed insulin resistance in our previous study." (PMID 38352704, 2024).